KRAS (KRas proto-oncogene, GTPase)
Diseases named in the same sentence as KRAS in open-access papers (continued):
Sharing a sentence is not in itself a finding about the gene and the disease.
cancer (continued). "The mutational activation of KRAS is one of most frequently events occurring in human cancers and causally related to tumorigenesis, thus KRAS is an effective antitumor drug target." (PMID 37261210, 2023). "Most common mutations in KRAS associated with cancer result in aberrant RAS activation, leading to uncontrolled cell growth, contributing to tumourigenesis." (PMID 36723696, 2023). "Oncogene KRAS mutations alter cancer cell metabolism by inducing upregulated transcription of glucose transporters and glycolytic enzymes." (PMID 37394582, 2023). "A breakthrough in RAS-targeting drug discovery was achieved for the KRAS G12C mutant, which accounts for 12% of all cancer-associated KRAS mutations." (PMID 37935773, 2023). "Activating mutations in KRAS are highly relevant to various cancers, driving persistent efforts toward the development of drugs that can effectively inhibit KRAS activity." (PMID 38069255, 2023). "The lung adenocarcinoma subgroup of NSCLC is the third cancer category with the most frequent mutations in KRAS." (PMID 36313934, 2023). "The development of KRAS G12C inhibitors has revolutionized drug development for KRAS-mutated cancers." (PMID 37190303, 2023). "KRAS is required for normal cell signaling, growth, proliferation, and apoptosis, and mutations in this gene have been linked to a variety of human cancers." (PMID 37505851, 2023). "These alkylating signatures targeted cancer driver mutations KRAS p.G12D, KRAS p.G13D, and PIK3CA p.E545K, as well as predicted poor survival in CRC patients." (PMID 37525147, 2023). "The mutational landscape of our LUAD cohort was very similar to what is expected for this cancer type, with KRAS being the top mutated gene (41%) followed by RYR2 (34%) and MUC16 (32%)." (PMID 37501683, 2023). "In pancreatic cancer, KRAS mutations lead to metabolic remodeling and upregulation of Nrf2, which impairs the effect of chemotherapy drugs on cancer cells." (PMID 37298157, 2023). "Broad-spectrum activity is seen in pancreatic, colorectal and NSCLC type cancers, presenting an exciting new therapeutic option for KRAS-mutated cancers." (PMID 37190303, 2023). "HRAS, referred to as oncogenic RAS with NRAS and KRAS, is one of the most frequently mutated driver proto-oncogenes in cancer." (PMID 36906552, 2023). "The combination of KRAS inhibitors with chemotherapies and immunotherapies holds enormous promise for improving outcomes for patients with KRAS-mutated cancer." (PMID 37190303, 2023). "The MAPK-pathway, for which KRAS is a defining molecule, constitutes a signalling cascade from the cell surface to the nucleus and is frequently mutated in various cancers." (PMID 37509363, 2023). "KRAS mutations occur in various cancer types and mutant KRAS sEVs comprise overexpressed GLUT-1 to facilitate glycolysis." (PMID 37208722, 2023). "SCNN1B expression was most closely associated with downregulated genes upon KRAS activation in cancer cell lines (FDR < 0.01)." (PMID 36564468, 2023). "KRAS is the most frequently mutated oncogene and a major driver of cancer (stemness), which has finally become a clinically validated drug-target, thanks to KRAS-G12C targeting sotorasib and adagrasib." (PMID 36688434, 2023). "In oncogene-addicted cancers (HER2-mutant cancer, oncogene-driven EGFR-positive, ALK-positive, or RET-positive NSCLC), current studies do not encourage the use of immune checkpoint inhibitors, with the exception of KRAS-mutated cancers." (PMID 36865093, 2023). "KRAS mutations are ubiquitous in benign and malignant tumors across several histological types at different anatomic sites." (PMID 36752878, 2023).
cancer (continued). "The KRAS G12D mutation is very frequent in many cancers, such as pancreatic, colon and lung, and has remained undruggable for the past three decades, due to its smooth surface and lack of suitable pockets." (PMID 36975507, 2023). "It is not fully understood why KRAS is more frequently mutated in cancer than the other RAS genes, NRAS and HRAS." (PMID 37370697, 2023). "For instance, KRAS has been implicated in driving an aberrant overexpression of TF, as well as in promoting TF release as active cargo of cancer-derived extracellular vesicles (EVs)." (PMID 38188342, 2023). "This group suggested that the potent oncogenicity of HRAS lead to cell cycle arrest and senescence, while the different codon usage of KRAS overcomes this issue becoming the most frequently mutated RAS in cancer." (PMID 37892237, 2023). "As a matter of fact, KRAS is a well-known oncogene, whose mutations or overexpression are common in various cancers." (PMID 37686696, 2023). "We observe consistent patterns of KRAS > NRAS»HRAS protein expression in cells that correlate with the rank order of Ras mutation frequencies in cancer." (PMID 36864243, 2023). "KRAS is most significant to us because it is often mutated to be overexpressed in a number of cancers, leading to excessive cancer proliferation." (PMID 36769189, 2023). "We targeted G12D and G12V, two of the most relevant KRAS mutations in cancer, and the two mutations most detected in PDAC." (PMID 37097304, 2023). "We also suggest utilizing these four flavonoids in the development of antibody-drug conjugates (ADCs) and proteolysis-targeting-chimera (PROTAC) technologies for the effective treatment of KRAS G12D mutated cancers in the near future." (PMID 36975507, 2023). "In YO cancer, variant KRAS–associated mortality risk was higher in distal tumors than proximal tumors." (PMID 38032636, 2023). "The activity of KRAS in the context of cancer risk factors in pre-malignant tissue would benefit from considerable further investigation." (PMID 37452870, 2023). "When mutated, KRAS can become an oncogene, driving uncontrolled cell growth and contributing to the development and progression of cancer." (PMID 38203635, 2023). "In the remaining two, a higher percentage of right-sided primaries was reported in KRAS G12C-mutated cancers." (PMID 37240418, 2023). "In recent years, researchers have attempted to repurpose antibody, e.g., cetuximab (CTX) that is ineffective for KRAS-mutated cancers, to deliver highly toxic drug to treat KRAS-driven cancers such as PDAC." (PMID 36831298, 2023). "The median cause-specific survival for KRAS variant vs KRAS wild type was 3.0 and 3.5 years in young-onset and 2.5 vs 3.4 years in late-onset cancer." (PMID 38032636, 2023). "The high prevalence of KRAS mutations has been identified to play an important role in the immunosuppressive TME in cancers, through actions such as inducing NLRP3 inflammasome activation and programmed death-ligand-1 (PD-L1) expression." (PMID 37110848, 2023). "This is the case with KRAS (Kirsten Ras oncogene), one of the most common mutated oncogenes in cancer." (PMID 37569407, 2023). "We evaluated this relationship since oncogenic KRAS has been implicated as a prognostic and predictive cancer biomarker." (PMID 37558751, 2023). "Promising clinical data are emerging for KRASG12C inhibitors, but treatment of KRAS-mutated cancer remains challenging." (PMID 37020037, 2023). "At the same time, we found that miR-204-3p inhibitor cancel the inhibition effect of silencing hsa_circ_0001846 on KRAS, and knockout of KRAS reversed the cancer-promoting effect caused by overexpression of hsa_circ_0001846." (PMID 38081815, 2023). "The patterns of Ras isoform expression that we observe potentially inform our understanding of why KRAS is more frequently mutated in cancer." (PMID 36864243, 2023).
cancer (continued). "It is worth mentioning the development of advanced cell therapies and cancer vaccines targeting mutated KRAS that are also under development and clinical assessment." (PMID 37376135, 2023). "Mutated KRAS drives a complex network of lipid metabolic rearrangements to support the adaptation of cancer cells to harsh environmental conditions and ensure their survival." (PMID 36675307, 2023). "For the diagnostic application of eccDNA we developed and tested a qPCR primer‐based SNP detection system, for the detection of two well‐established cancer‐causing KRAS mutations (G12V and G12R) on circular DNA." (PMID 37602814, 2023). "In contrast, transcriptional changes associated with both E2F targets and the G2M checkpoint were regulated by SOS2KO but not acute SOS1i treatment, consistent with previous studies showing a role for SOS2 in 3D spheroid growth of KRAS-mutated cancer cells." (PMID 38106234, 2023). "It is important to underline that NQO1 expression is highly activated in cancer cells with mutant Kirsten rat sarcoma viral oncogene homolog (KRAS) signaling." (PMID 37175546, 2023). "Specifically, the distribution of KRAS mutations shows significant preferences in different human cancers." (PMID 37110848, 2023). "The following end points have been evaluated: (a) DNA methylation of the let-7a gene promoter by bisulphite-PCR and pyrosequencing; (b) let-7a expression by qPCR; (c) KRAS mutation by DNA pyrosequencing; (d) cancer incidence by histopathological examination." (PMID 37511536, 2023). "KRAS oncogenic pathway affected TME via modulation of cancer-associated fibroblasts and immune cells." (PMID 36874015, 2023). "Supporting this, cancer cells with KRAS mutations have been shown to have increased levels of AGO2 phosphorylation at serine 387 (AGO2S387)." (PMID 37686149, 2023). "The cell‐intrinsic mechanisms underlying the role of mutant KRAS in human cancer pathogenesis have been widely studied." (PMID 36599679, 2023). "Our results build on these previous findings and further underscore the poor prognosis and high unmet medical need that exists in patients with aNSCLC with co-occurring mutations in STK11 and KEAP1, with either KRAS WT cancer or KRAS G12C–positive cancer." (PMID 37069542, 2023). "KRAS is commonly mutated in human cancers; however, the percentage of mutations varies between cancer types." (PMID 37296881, 2023). "KRAS mutations are predominant in cancer, particularly in PDAC, and 90% to 95% of PDACs have this mutation." (PMID 37158894, 2023). "RMC-6236 is the first multi-targeting KRAS inhibitor against G12C, G12D, G12V and G12X-mutated KRAS cancers." (PMID 37190303, 2023). "BI-3406 is an inhibitor of SOS1, which is effective at nanomolar concentrations and sufficiently antagonizes GEF to dampen MAPK pathway activity in KRAS-mutated cancers." (PMID 37190303, 2023). "The difference between the cancer-free and the cancer-bearing mice consisted in the relationship between the let-7a downregulation intensity and the KRAS mutation amount." (PMID 37511536, 2023). "For example, CancerSEEK, a pan-cancer screening test, demonstrated 72% sensitivity and >99% specificity in patients with symptomatic PDAC, which combines cancer-associated genes and proteins, including KRAS and CA 19-9." (PMID 36673023, 2023). "Another drug that has been proposed for indirect therapy of KRAS-mutated cancers due to its RAF kinase inhibitory activity is sorafenib, approved for the treatment of advanced hepatocellular carcinoma." (PMID 37376135, 2023). "Apoptosis, EMT, KRAS signalling, hypoxia, and angiogenesis were some of the key cancer-associated processes enhanced in 3D growth." (PMID 37444459, 2023).
cancer (continued). "Rat sarcoma virus oncogene homologues (RAS) and KRAS are among the most common RAS genes associated with human cancer." (PMID 37261210, 2023). "UGCG and B4GALT5, which encodes LCS, were significantly elevated in KRAS mutant cancers (n = ~730), and combined high expression of UGCG and B4GALT5 correlated with shortened 5-year survival." (PMID 36709325, 2023). "RAS mutations are the most common oncogenic mutations in human cancers and KRAS has the highest frequency among other members of the RAS family in NSCLC." (PMID 36899885, 2023). "In vivo, RMC-6291(200 mg/kg) resulted in a 68% Objective Response Rate (ORR), while the Adagrasib (100 mg/kg) treatment resulted in 43%, in a range of NSCLC KRAS G12C-mutated cancers." (PMID 37190303, 2023). "Supporting this, previous studies have shown that miRNA biogenesis and global miRNA expression levels are significantly dysregulated in cancers harboring KRAS mutations." (PMID 37686149, 2023). "Recently, a germline, inherited variant in KRAS, referred to as the KRAS-variant, was identified as the first example of an inherited miRNA binding-site pathogenic variant in cancer." (PMID 37728512, 2023). "This commentary highlights the history of the research that led to this breakthrough that will help many patients with KRAS-mutated cancers to live longer and better." (PMID 36933199, 2023). "The receptor tyrosine kinase/RAS/MAP kinase (MAPK) pathway is an oncogenic pathway with widespread aberrancies in human cancers; indeed, 20%-30% of cancer patients harbor RAS (KRAS, HRAS, or NRAS) mutations." (PMID 37705755, 2023). "Profiling was carried out using Duplex-seq, which covers a broader range of mutations (EGFR exon 18, 19, 20 and 21, KRAS exon 2 and 3 and other cancer genes)." (PMID 37020004, 2023). "Cancer markers, such as KRAS G12D, EGFR L858R, and EGFR T790M mutations, containing 0.1% VAF, were clearly detected in under 2 h with a high reliability comparable with that of ddPCR." (PMID 36979592, 2023). "Since this is a field in clear expansion, in the present work, the most recent studies aiming to treat KRAS-mutated cancers using nanotechnology-based approaches able to target KRAS will be presented." (PMID 37376135, 2023). "This cancer presents a low frequency of PIK3CA mutations (5%) but a high percentage of KRAS oncogenic alterations (90%), responsible for the global activation of the PI3K/AKT pathway." (PMID 36765741, 2023). "KRAS mutations increase glutamine demand in cancer cells that use glutamine to accelerate energy metabolism and maintain redox homeostasis." (PMID 36959802, 2023). "In cancer tumorigenesis, KRAS mutations typically increase the steady-state levels of the active form, driving protumorigenic pathways, such as the mitogen-activated protein kinase (MAPK) and Phosphatidylinositol 3-kinase (PI3K) pathways." (PMID 37298264, 2023). "Classic efforts have identified a “long-tail” distribution of cancer driver mutations, where some mutations (e.g., KRAS G12D) are highly prevalent, and other mutations are extraordinarily rare." (PMID 38062391, 2023). "Prevalence Ratios (PRs) for the presence of somatic KRAS mutations were estimated using modified Poisson regression models adjusted for age, sex, smoking status, race/ethnicity, educational attainment, cancer stage, and histology." (PMID 36383274, 2023). "It is noteworthy that while the KRAS-specific degrader was able to eliminate both wild-type and variant KRAS, it only inhibited cell proliferation in cancer cell lines with the KRAS-variant present." (PMID 37592990, 2023). "Current therapeutic approaches for cancer, e.g., monochemotherapy targeting KRAS mutations and a combination of chemotherapy with radiotherapy/immunotherapy, have exhibited limited efficacy in patients with PDAC." (PMID 38268915, 2023). "With high RAS activation due to mutations that render KRAS constitutively active, xCT transcription can be promoted to meet the need for cancer cell homeostasis." (PMID 37604805, 2023).
cancer (continued). "For example, KRAS mutations promote inflammation and inhibit the immune response, eventually leading to cancer progression." (PMID 36926333, 2023). "Genomic profiles of cancer patients identified that tumor-induced mutations in KRAS, STK11, KEAP1, CDKN2B, CTNNB1, and MET are significantly associated with cancer-associated thrombosis." (PMID 37046748, 2023). "In these studies, cancer-derived cfDNA containing KRAS hotspot mutations were enriched in ultrashort sizes (< 100 bp)." (PMID 37898819, 2023). "KRAS gene is the most frequently mutated oncogene in cancer, 95% of PDAC patients show KRAS oncogene mutations, and KRAS mutations are often associated with poor prognosis and drug resistance of tumors." (PMID 37287989, 2023). "The present work aims to summarize the most recent advances related to the use of nanotechnology for the development of new therapeutic strategies against KRAS-mutated cancers." (PMID 37376135, 2023). "Another promising strategy of gene therapy against KRAS-mutated cancer consists in the use of microRNAs (miRs)." (PMID 37376135, 2023). "More precisely, a SERS chip with the ability to detect specific KRAS mutations and differentiate between wild-type and mutated KRAS genes in different cancer cells was developed." (PMID 36900154, 2023). "KRAS mutation was found more in well and moderately (54.6% and 54.1% respectively) than in poorly differentiated carcinoma (34.3%)." (PMID 37277698, 2023). "KRAS mutations remain the most frequently observed alterations in patients with carcinomas (64.9%) and mucinous borderline tumors (92.3%)." (PMID 37185420, 2023). "In total, there were 444 carcinoma cell lines with expression, exon mutation and dependency data, of which 106 had KRAS mutations." (PMID 37141389, 2023). "It has been shown that BRAF or KRAS mutations in initiated cells co-operate with silenced TSGs by promoter hypermethylation to progress toward carcinoma formation." (PMID 37772997, 2023). "In this study we identified mutations in three known human mutation hotspots PIK3CA p.H1047R, PIK3CA p.E545D and KRAS p.G12V/D, which have all previously been shown to be implicated in human breast neoplasia and even other types of carcinomas in humans." (PMID 36635367, 2023). "A retrospective overview showed that the cetuximab treatment is ineffective in cancers with KRAS mutations, and testing of KRAS genotype as a predictive biomarker is necessary for cetuximab or panitumumab therapy in CRC." (PMID 36359850, 2022). "As a proof of concept, we profiled three cancer cell lines with different oncogenic KRAS mutations by treatment with AMG-510 at various doses." (PMID 35953080, 2022). "In this study, we observed that HOXB9 gene was not only significantly upregulated in cancer vs. normal colon, but its levels were significantly increased when KRAS mutations were present." (PMID 35216396, 2022). "Immune cold TMEs were predominantly enriched for signaling pathways typically associated with cancer progression or immune evasion, such as epithelial–mesenchymal transition and KRAS downsignaling." (PMID 36281356, 2022). "RAS is the most frequently mutated oncogene in cancer and about the 45% of CRCs harbor KRAS mutations." (PMID 35158939, 2022). "G12D, a single amino acid mutation of KRAS, is the most frequent mutation and is seen in diverse cancers such as pancreatic ductal adenocarcinomas." (PMID 35725570, 2022). "KRAS is the most mutated oncogene in cancer, with mutations in non-small cell lung cancers (NSCLC) (20-25%), colorectal cancers (30–50%) and pancreatic ductal adenocarcinoma (95%)." (PMID 36015212, 2022). "KRAS is one of the most frequently mutated oncogenes in cancer, and activating mutations are present in ∼2.5 million new cancer cases per year worldwide." (PMID 36065754, 2022).